IGF2R (insulin like growth factor 2 receptor)
Description:
Mediates the transport of phosphorylated lysosomal enzymes from the Golgi complex and the cell surface to lysosomes. Lysosomal enzymes bearing phosphomannosyl residues bind specifically to mannose-6-phosphate receptors in the Golgi apparatus and the resulting receptor-ligand complex is transported to an acidic prelysosomal compartment where the low pH mediates the dissociation of the complex. The receptor is then recycled back to the Golgi for another round of trafficking through its binding to the retromer. This receptor also binds IGF2. Acts as a positive regulator of T-cell coactivation by binding DPP4.
Synonyms: CI-MPR; MPR 300; M6P/IGF2R; CD222; MPRI; MPR1; CIMPR; M6P-R; CI-M6PR; MPR300
Tractability: Antibody: UniProt places it where antibodies can reach, with high confidence; its Gene Ontology location is reachable by antibodies, with high confidence; UniProt predicts a signal peptide or a membrane-spanning region. PROTAC: ubiquitination databases record sites on it; its protein half-life has been measured; a small molecule that binds it is known.
Target class: Membrane receptor
Gene: Protein-coding gene on chromosome 6 (159,969,082 to 160,113,507, forward strand). Ensembl gene ENSG00000197081.
Subcellular location: Golgi apparatus membrane; Endosome membrane
Subcellular location (Human Protein Atlas): Golgi apparatus; Vesicles
Pathways (Reactome):
Vesicle-mediated transport: Cargo recognition for clathrin-mediated endocytosis; Clathrin-mediated endocytosis; Golgi Associated Vesicle Biogenesis; Retrograde transport at the Trans-Golgi-Network
Immune System: Neutrophil degranulation
Gene Ontology:
Molecular function: cargo receptor activity; identical protein binding; phosphoprotein binding; protein binding; retromer complex binding; insulin-like growth factor binding; signaling receptor activity; D-mannose binding; enzyme binding; G-protein alpha-subunit binding; insulin-like growth factor II binding; retinoic acid binding
Biological process: Golgi to lysosome transport; host-mediated activation of viral process; protein targeting to lysosome; signal transduction; animal organ regeneration; G protein-coupled receptor signaling pathway; liver development; lysosomal transport; positive regulation of apoptotic process; post-embryonic development; regulation of apoptotic process; response to retinoic acid; response to tetrachloromethane; spermatogenesis
Cellular component: cell surface; early endosome; endocytic vesicle; endosome; endosome membrane; extracellular exosome; focal adhesion; Golgi apparatus; Golgi membrane; late endosome; membrane; trans-Golgi network; trans-Golgi network transport vesicle; clathrin-coated endocytic vesicle membrane; plasma membrane; secretory granule membrane; trans-Golgi network membrane; transport vesicle; clathrin coat; cytosol; endomembrane system; extracellular region; nuclear envelope lumen; nucleus; perinuclear region of cytoplasm
Genetic constraint (gnomAD): Loss-of-function variants: 76 observed, 218.55 expected, observed/expected ratio (o/e) 0.35, 90% interval 0.29 to 0.42. The upper end of that interval is the gene's LOEUF score, 0.42, which puts it in group 1 of 6, group 1 being the genes least tolerant of losing a copy. Missense variants: 2,478 observed, 2,883.9 expected, observed/expected ratio (o/e) 0.86, 90% interval 0.83 to 0.89. Synonymous variants: 1,191 observed, 1,150.2 expected, observed/expected ratio (o/e) 1.04, 90% interval 0.99 to 1.09.
Homologues: Orthologues: chimpanzee IGF2R (99% identical), macaque IGF2R (95% identical), dog IGF2R (86% identical), pig IGF2R (82% identical), mouse Igf2r (81% identical), guinea pig IGF2R (81% identical), rat Igf2r (81% identical), rabbit IGF2R (75% identical), tropical clawed frog igf2r (53% identical), zebrafish igf2r (51% identical), Drosophila melanogaster Lerp (11% identical).
Diseases named in the same sentence as IGF2R in open-access papers:
IGF2R is named in the same sentence as 136 diseases in open-access papers, as found by Europe PMC text mining. Sharing a sentence is not in itself a finding about the gene and the disease. The quoted sentences say what the papers report.
breast carcinoma (25 papers, 1994 to 2026). "The deletion of the IGF2R allele has been shown to be an early event in the etiology of breast cancer as a tumor suppressor." (PMID 36330486, 2022). "In summary, by analyzing patients from the TCGA and GEO databases, we found that IGF2R is a gene that is associated with a poor prognosis in patients with breast cancer." (PMID 36330486, 2022). "For example, a constitutive YAC transgenic Igf2r gain of function model was shown to rescue Thp (Igf2r loss of function), and also mammary tumour progression in an Igf2 induced mammary tumour model." (PMID 31388182, 2019). "Some tumors, including hepatocellular carcinoma and breast cancer, have been associated with loss of heterozygosity of the IGF2R gene." (PMID 25424625, 2014). "Loss of heterozygosity (LOH) of the M6P/IGF2R has been linked to liver and breast cancers, whereas somatic mutations of the M6P/IGF2R have been found in cancers of the prostate, lung, endometrium, brain, stomach and colorectum." (PMID 20302654, 2010). "We have sought to confirm that allelic loss of IGF2R is an early event in the aetiology of breast cancer by screening a group of 'early' lesions for LOH at a polymorphic microsatellite marker within the IGF2R gene using polymerase chain reaction (PCR)." (PMID 9413941, 1997). "In addition, we revealed that the higher expression group of the IGF2R gene is significantly associated with the poor survival of breast cancer patients." (PMID 37684436, 2023). "In addition, low levels of IGF2R have been associated with a poor prognosis in patients with breast cancer." (PMID 36330486, 2022). "Notably, four lncRNAs (lnc-RPRD2-3:1, lnc-KCNA5-3:4, lnc-CFP-1:1 and lnc-CD164L2-1:1) correlated strongly with the mutation status of IGF2R, a tumor suppressor commonly mutated in human liver and breast cancer." (PMID 29416609, 2018). "Finally, human tumors (including breast carcinomas) show genetic loss or mutation of IGF2R." (PMID 32117864, 2020). "Experimental validation confirmed the downregulation of key genes such as SAV1 and IGF2R in breast cancer cells." (PMID 41511940, 2026). "LEF1 regulates breast cancer cell proliferation, and IGF2R enhances tumor cell invasion and migration and serves as a poor prognostic marker in triple-negative breast cancer patients." (PMID 41511940, 2026). "The expression levels of SAV1 and IGF2R were markedly reduced in breast cancer cells compared to MCF10A." (PMID 41511940, 2026). "Experimental validation confirmed that SAV1 and IGF2R were significantly downregulated in breast cancer cell lines, consistent with public datasets, underscoring their biological relevance." (PMID 41511940, 2026). "In the circulation, IGF2R expressing lymphocytes were detected both in healthy donors (mean 18.6 ± 7.6%) and breast cancer patients (mean 22.7 ± 12.4) with high PD-1 expression." (PMID 40756372, 2025). "It indicates that the doxorubicin induces the dysregulation of hiPSC-CMs derived RAD9A, HSPA1B, GATA2, IGF2R, CD200, ERCC8, and BCL11A genes that are associated with the pathogenesis of doxorubicin-induced cardiotoxicity in breast cancer patients." (PMID 37684436, 2023). "In the METABRIC database, the expression of IGF2R distinguished patients with breast cancer with a poor prognosis from those with a more favorable prognosis and was highly expressed in patients with TNBC." (PMID 36330486, 2022). "Therefore, we speculate that IGF2R may cause breast cancer immune escape through CD19+ TILs." (PMID 36330486, 2022). "The clinical data and insulin-like growth factor 2 receptor (IGF2R) expression profiles of patients with breast cancer were extracted from METABRIC." (PMID 36330486, 2022). "In the METABRIC dataset including 1,818 patients with breast cancer, the OS was lower in the patients with a higher IGF2R expression level compared with the patients with a lower IGF2R expression level (P = 0.008)." (PMID 36330486, 2022).
breast carcinoma (continued). "Of the 1,098 patients with breast cancer in the TCGA dataset, those with a higher level of IGF2R had a lower OS compared with those with a lower level of IGF2R (P < 0.001)." (PMID 36330486, 2022). "For example, the H19/insulin-like growth factor 2 (IGF2) and insulin-like growth factor 2 receptor (IGF2R) imprinted gene network is involved in colorectal, prostate, lung and breast cancers." (PMID 32448196, 2020). "Igf1R mRNA expression level was similar in the two cell types; however, melanoma cells expressed almost two times more Igf2R mRNA than breast cancer cells." (PMID 32534480, 2020). "There are yet no known studies to characterize the role of IGF2 action in melanoma but some isolated studies have pointed at a tumor suppressing role of IGF2 in mammary carcinoma cells expressing IGF2R." (PMID 28223541, 2017). "In contrast, the anti-invasive effects of M6P/IGF2R in breast cancer cells have been attributed to decreased IGF-II bioavailability." (PMID 22521359, 2012). "Similarly, LOI resulting in biallelic silencing of genes like PEG3, P57, and IGF2R has been observed in oligodendrogliomas, breast cancer, and hepatocellular carcinomas, respectively." (PMID 39941009, 2025). "IR is known to be overexpressed in breast cancer, while IGF2-R is correlated to poor prognosis in patients with triple negative breast cancer but their roles in HNPGN is unknown." (PMID 39619326, 2024). "In addition, luminal A and luminal B patients with a high expression of IGF1R and a low expression of IGF2R had significantly higher survival rates than patients with other types of breast cancer." (PMID 36330486, 2022). "However, the role of IGF2R in the immunotherapy of patients with breast cancer requires further study." (PMID 36330486, 2022). "Furthermore, from the breast cancer database of Peking Union Medical College Hospital, we identified the relationships between IGF2R expression and the clinical characteristics of TILs." (PMID 36330486, 2022). "Furthermore, in some cancers such as mammary tumors, IGF2R behaves as a tumor suppressor gene, whereas in other cancers such as cervical tumors or glioblastomas, IGF2R acts as an oncogene." (PMID 32075092, 2020). "However, studies in choriocarcinoma and breast cancer cells have demonstrated that a decrease in M6P/IGF2R expression enhances tumor cell growth, whereas overexpression of the receptor causes the opposite effect." (PMID 22521359, 2012). "However, IGF2R is overexpressed in HR-negative breast cancer." (PMID 36330486, 2022). "In contrast, TLR5 and IGF2R are consistently upregulated in heart failure patients not who have breast cancer." (PMID 37684436, 2023). "Finally, we validated the expression level of immune-related genes in breast cancer patients-derived cardiomyocytes with doxorubicin-induced cardiotoxicity and found that the level of RAD9A, HSPA1B, GATA2, IGF2R, CD200, ERCC8, and BCL11A genes are consistently dysregulated." (PMID 37684436, 2023). "Finally, we validated that RAD9A, HSPA1B, GATA2, IGF2R, CD200, ERCC8, and BCL11A genes are consistently dysregulated in the doxorubicin-induced human-induced pluripotent stem cell-derived cardiomyocytes (hiPSC-CMs) derived from breast cancer patients." (PMID 37684436, 2023).
melanoma (20 papers, 2012 to 2025). A malignant, usually aggressive tumor composed of atypical, neoplastic melanocytes. "Recently, IGF2R mutation was documented in 32% of 41 mucosal melanomas in comparison to 6% of 48 cutaneous melanomas." (PMID 34571863, 2021). "Melanosomal-MIR211 released from melanoma cells are transferred into the surrounding primary skin fibroblasts and which then induce their reprogramming into cancer-associated fibroblasts (CAFs) by targeting the IGF2R mRNA and through regulating MAPK signaling." (PMID 33628737, 2020). "The significance of frequently mutated IGF2R in mucosal melanomas remains unclear." (PMID 34571863, 2021). "We observed that inhibiting the expression of the alpha and beta subunit of GNPT, in WM1716 as well as WM1745, phenocopied the effect of IGF2R inhibition on melanoma invasion." (PMID 38750105, 2024). "Taken together, our results revealed the association of lysosome function to melanoma metastasis via the GNPTAB, IGF2R, and TFEB axis." (PMID 38750105, 2024). "We performed invasion assays on WM1716 human melanoma cells depleted for IGF2R and supplemented the media with either active TGFβ or the activated form of plasminogen, plasmin." (PMID 38750105, 2024). "Altogether those results indicate that inhibiting IGF2R expression reduces melanoma invasive potential by impairing hydrolase transport to the lysosomes." (PMID 38750105, 2024). "The role of IGF2R in melanoma is rather unexpected, since this gene is generally considered as a tumor suppressor because loss of heterozygosity, SNPs, and somatic mutations of IGF2R are associated with several cancers." (PMID 38750105, 2024). "For example, the high level of miR-211 in melanoma-derived exosomes directly decreases the expression of insulin-like growth factor 2 receptor (IGF2R) in fibroblasts, thus, upregulating the MAPK signaling pathway to induce the primary CAFs reprogramming." (PMID 36499102, 2022). "As shown in cutaneous melanoma, reduced expression of IGF2R inhibits the metastatic potential of melanoma cells." (PMID 34571863, 2021). "In this study, we analyzed the prognostic role of NRAS, KIT, BRAF, IGF2R and SF3B1 mutations in a series of mucosal melanomas." (PMID 34571863, 2021). "EV-miR-211 from melanoma cells reprograms primary fibroblasts into CAFs by targeting IGF2R, thereby potentially fostering dermal tumor niches and melanoma invasion." (PMID 32503543, 2020). "In our analysis, we found significant suppression of IGF2R on all melanoma cells following GHRKD but a significant rise in IGF1R and IR RNA levels following GHRKD especially when treated with excess GH." (PMID 28223541, 2017). "As we report here, the melanoma cells indeed appear to be in a state of heightened insulin/IGF sensitivity via abundant expression of IR, IGF1R and IGF2R as seen in all four melanoma cells in this study." (PMID 28223541, 2017). "their cognate receptors (IR, IGF1R, IGF2R and heterologous pairs) and binding proteins (IGFBPs) are important determinants of melanoma disease progression." (PMID 28223541, 2017). "We found high levels of RNA of the corresponding cognate receptors – IR, IGF1R, and IGF2R in all the four melanoma cells studied here." (PMID 28223541, 2017). "Expression levels of miR-211 are inversely related to melanoma cell migration and invasion, and it has been shown to function as a tumour-suppressor through target genes including IGF2R, TGFBR2 and NFAT5." (PMID 27852308, 2016). "It has been well documented that miR-211 is a lineage-specific miRNA which is highly expressed in the melanocytic lineage and has been associated with melanoma cell invasiveness via its direct regulation of POU3F2 (BRN2), IGF2R, TGFBR2, NFAT5, and NUAK1." (PMID 25980496, 2015). "Enhanced M6PR and IGF2R may facilitate anterograde and retrograde transport between lysosomes and the trans-Golgi network in melanoma cells to maintain the composition and function of the constituent organelles." (PMID 41155412, 2025).
melanoma (continued). "Here, we found that perturbing hydrolase transport to lysosomes by blocking either the expression of IGF2R, the main receptor responsible for their trafficking, or GNPT, a transferase involved in the addition of the specific tag recognized by IGF2R, reduces melanoma invasiveness potential." (PMID 38750105, 2024). "Indeed, GNPTAB depletion by siRNAs, phenocopied the depletion of IGF2R and reduced melanoma invasiveness potential." (PMID 38750105, 2024). "Among those targets, the expression of IGF2R has been shown to be necessary for melanoma invasion by an unknown mechanism." (PMID 38750105, 2024). "Since IGF2R is a tumor suppressor in some tumor types, we wanted to determine whether our observations were restricted to melanoma." (PMID 38750105, 2024). "Next, we investigated if impairing the role of IGF2R in hydrolase transport could affect melanoma invasiveness potential." (PMID 38750105, 2024). "Although our results do not confirm the direct role of IGF2R mutations in driving mucosal melanoma development, there are data suggesting its more complex role." (PMID 34571863, 2021). "This might partly explain the resistance of melanoma cells to IGFs, because IGF2R directs IGF2 to lysosomes to attenuate signaling." (PMID 32534480, 2020). "In melanoma cells, the loss of IGF2R expression also results in an increase in the secretion of proteins with an m6p tag, but hydrolases are activated at acidic pH, which can be found in the hepatocellular microenvironment but not in melanomas." (PMID 38750105, 2024). "MiR-211 is encoded within the sixth intron of TRPM1, a candidate suppressor of melanoma metastasis, and previous researches demonstrated that overexpression of miR-211 inhibited both anchorage-independent colony formation and invasion, through regulation of IGF2R, TGFBR2, NFAT5 and BRN2." (PMID 23155457, 2012). "Increased expression of M6PR, IGF2R, and SORT1 has been found in melanoma across different independent gene expression datasets." (PMID 41155412, 2025). "The cellular uptake of rhARSB in the melanoma cells is mediated by insulin-like growth factor 2 receptor (IGF2R), the paternally imprinted, cation-independent mannose-6-phosphate receptor." (PMID 40562100, 2025). "Some of the researchers implied it as a tumor suppressor by targeting oncogenic genes such as IGF2R, TGFBR2 and NFAT5 in melanoma." (PMID 28924391, 2017). "In agreement with recent comprehensive reports of IGF gene expressions in melanoma, we found low levels of IGF1 and very high levels (25-fold greater than GHR) of IGF1R and IGF2R expression (Figure 5a1)." (PMID 28223541, 2017). "Taken together, our data demonstrate that activation of TGFβ or plasminogen by IGF2R is not necessary for melanoma invasion." (PMID 38750105, 2024). "Regarding IGF2R, it has been found overexpressed in carcinomas of the larynx, uterine cervix, or bladder, as well as in melanoma, as compared to the non-cancerous peritumoral tissue." (PMID 39201614, 2024). "Unlike our findings in melanoma, IGF2R has been described to be a tumor suppressor in gastrointestinal and breast cancer, we therefore investigated the consequences of blocking the hydrolase transport machinery on non-melanoma cancer types." (PMID 38750105, 2024). "Further, melanosomal microRNA-211 transferred into primary fibroblasts directly targeted insulin like growth factor 2 receptor (IGF2R) and activated mitogen-activated protein kinase (MAPK) signaling, thus triggering changes and reciprocally encouraging melanoma growth and invasion." (PMID 33869017, 2021). "Interestingly, we observed consistent expression of GH transcript in the melanoma cells as well as marked modulation of the IGF receptors and binding proteins (IGF1R, IGF2R, IR, IGFBP2, IGFBP3) and the oncogenic HGF-MET mRNA, in response to excess GH or GHRKD." (PMID 28223541, 2017).
melanoma (continued). "Since this receptor is modular and binds different ligands, we reasoned that it could be feasible to block only the function involved in melanoma metastasis without affecting other cellular function regulated by IGF2R." (PMID 38750105, 2024). "Due to this reasoning, we directly tested whether TGFβ and plasminogen were involved in melanoma invasion and we observed that neither of the activated factors alone were able to restore melanoma invasion upon IGF2R knockdown." (PMID 38750105, 2024). "Furthermore, high expression of IGF2R was correlated with good prognosis in renal cancer and melanoma; however, for the latter, this was not significant (log-rank test)." (PMID 31748500, 2019).